CXCL3 (C-X-C motif chemokine ligand 3)
Diseases named in the same sentence as CXCL3 in open-access papers (continued):
Sharing a sentence is not in itself a finding about the gene and the disease.
periodontitis (9 papers, 2020 to 2026). An acute or chronic inflammatory process that affects the tissues that surround and support the teeth. "In the late stages, S100a8 and S100a9, which encode damage-associated molecular patterns, and Cxcl5 and Cxcl3, which encode chemokines, are prominently upregulated, highlighting the persistent recruitment of neutrophils, a hallmark of periodontitis." (PMID 40076622, 2025). "Our scRNA-seq analysis revealed that macrophages expressed Ccl2, Ccl9, Cxcl4, and Cxcl6, and neutrophils expressed Ccl3, Ccl4, Ccl6, Cxcl2, and Cxcl3 throughout periodontitis development." (PMID 38015204, 2023). "IL1A, IL1B, CXCL1, and CXCL3 displayed some correlation with highly infected cells —mostly suprabasal cells, likely explaining the differentiation effects predicted for these cells in periodontitis." (PMID 38876998, 2024). "Moreover, PRF membranes increased chemokines CCL2, CCL7, CXCL2, and CXCL3, most of which are highly expressed in periodontitis fibroblasts." (PMID 39120336, 2024). "CXCL1, CXCL3, CXCL8, CSF3, IL1A, IL1B, and IL1RN all increased in JKs in periodontitis as predicted by our atlas/DEG analyses; alternatively, SKs were relatively less active compared to JKs." (PMID 38876998, 2024). "Higher levels of CXCL1 and other chemokines were found in human and rat’s gingiva from sites of periodontitis as compared with healthy sites, and in vitro, biofilms can provoke CXCL1, CXCL3, and CXCL8 expression in epithelial cells." (PMID 37762294, 2023). "In addition to classical pro-inflammatory cytokines, our cytokine array analysis revealed significant upregulation of several chemokines in ligature-induced periodontitis, including thymus chemokine (CCL25), CINC-1 (CXCL1), and CINC-2α/β (CXCL3)." (PMID 41583507, 2026). "Similarly, keratinocytes in periodontitis patients show increased expression of CXCL1, CXCL3, CXCL8, CXCL13, and CCL20, suggesting that chemokine expression in gingival fibroblasts and epithelial cells drives chronic periodontitis." (PMID 40565042, 2025). "Moreover, chemokines such as CXCL8, CXCL10, CXCL12, and CCL5 accumulate in the crevicular fluid of periodontitis patients and their source might be attributed to fibroblasts at least for CXCL2, CXCL3, CXCL8, CXCL9, CXCL10, CXCL12, and CXCL16." (PMID 37762294, 2023).
viral infection (9 papers, 2010 to 2025). "In a BCSFB model using human choroid plexus papilloma cells, a viral infection with Echovirus 30 showed an enhanced secretion of Cxcl1, Cxcl2, Cxcl3, and Ccl5." (PMID 32645014, 2020). "The viral infection group exhibited significantly increased mRNA levels of IL-6, TNFα, CXCL-2, CXCL-3, CXCL-8/IL-8, and CXCL-10 compared to the NC group." (PMID 40872743, 2025). "Hierarchical clustering identified a distinctive innate immune signature in bite sites that was dominated by neutrophil-attracting chemokines (CXCL1, CXCL2, CXCL3, and CXCL5) and the cytokines IL-1β and IL-6, which were not significantly induced by virus infection alone." (PMID 27332734, 2016).
colon adenocarcinoma (8 papers, 2014 to 2023). "Survival analysis on GEPIA using colon adenocarcinoma data set screened 5 genes CXCL3, IL1B, IL1A, MET and TNS1 that have significant log rank p value in Kaplan–Meier survival analysis." (PMID 34083590, 2021). "Besides, a recent study identified CXCL3 and CXCL8 as diagnostic and prognostic genes in colon adenocarcinoma via integrating mRNA expression and DNA methylation profiles." (PMID 33330065, 2020). "For example, in colon adenocarcinoma, the expression of CXCL1, CXCL2, and CXCL3 negatively correlated with EMT, whereas the expression levels of CXCL5, CXCL6, PPBP, and CXCL8 positively correlated with EMT." (PMID 37686093, 2023). "In colon adenocarcinoma, CXCL1, CXCL2, and CXCL3 negatively correlated with EMT, while CXCL5, CXCL6, PPBP, and CXCL8 positively correlated with EMT." (PMID 37686093, 2023). "Earlier studies indicated that the expression of CXCL3 and CXCL8 in colon adenocarcinoma tissue increased significantly when compared with normal tissue." (PMID 33489879, 2020). "CXCL3 and CXCL8 are the key genes that affect the diagnosis and prognosis of colon adenocarcinoma." (PMID 35802745, 2022). "Human colon adenocarcinoma, which was used as the positive control sample, also expressed CXCL3 in the cytoplasm, whereas the negative control sample showed no immunochemical reaction." (PMID 25485631, 2014). "However, the expression profile of CXCL3 and the exact molecular mechanism behind the role of CXCL3 in colon adenocarcinoma (COAD) has not been fully elucidated." (PMID 38031087, 2023).
glioma (8 papers, 2021 to 2025). A benign or malignant brain and spinal cord tumor that arises from glial cells (astrocytes, oligodendrocytes, ependymal cells). "These tumors are lower grade glioma (in the case of CXCL3 and CXCL5) and diffuse large B-cell lymphoma (in the case of CXCL2 and CXCL3)." (PMID 37686093, 2023). "Neutrophils are recruited to glioma inflammatory regions by chemokines such as CXCL1, CXCL2, CXCL3, CXCL5, CXCL6, IL-8 (CXCL8), and IL-1β, which are secreted by glioma cells." (PMID 41272822, 2025). "In glioma cells, CD133, a cancer stem cell marker, raises the expression of IL-1β and its downstream chemokines, including CCL3, CXCL3, and CXCL5." (PMID 33429364, 2021). "The expression of CXCL3 was found to be about a hundred times higher in glioma with ITN than without ITN." (PMID 37465363, 2023). "However, the expression of CXCL3 was not related to the prognosis of glioma patients in the TCGA dataset, possibly because of the relatively lower expression level." (PMID 37465363, 2023). "In addition, C–X–C motif chemokine receptor 4 (CXCR4), C–X–C motif ligand 3 (CXCL3), and matrix metallopeptidase 7 (MMP7), also considered as positively correlated genes, were reported as oncogenic genes and facilitate growth, invasion, migration, and chemoresistance in gliomas." (PMID 34868960, 2021).
colitis (7 papers, 2019 to 2025). Inflammation of the colon. "Similar to our observations in human UC, there was significant upregulation of the neutrophil-active chemokines Cxcl1, Cxcl2, Cxcl3 and Cxcl5 across all models of colitis tested, indicating that this core chemokine module is conserved in colitis development across species." (PMID 36192482, 2022). "Bulk RNA sequencing of colon tissues from FLNAR and FLNAQ animals on day 10 of DSS-induced colitis (the peak of disease) confirmed that FLNAR mice had less inflammation as indicated by a reduced expression of inflammatory genes (Il1b, Cxcl3, Cxcl2, or Trem1)." (PMID 40471139, 2025). "Moreover, the intestinal cells have up-regulation of pro-inflammatory chemokines like C-X-C motif chemokine ligand (CXCL) 1 (CXCL1), CXCL3, and CXCL8, which only perpetuates the inflammatory cycle of colitis." (PMID 36677021, 2023). "More importantly, mesalazine treatment reversed the suppressive effect of immune responsive genes, including chemokine (C–X–C motif) ligand (CXCL3), chemokine (C–C motif) ligand (CCL11 and CCL21), chemokine receptor (CXCR2), and colony-stimulating factor (CSF3) in the DSS-induced colitis model." (PMID 34456974, 2021).
gastric cancer (7 papers, 2014 to 2024). A primary or metastatic malignant neoplasm involving the stomach. "CXCL3 protein levels in the supernatant of CD36 overexpressed gastric cancer cells also decreased." (PMID 37781029, 2023). "Interestingly, expression of the chemokine (C-X-C motif) receptor 2 (CXCR2) ligands CXCL2 and CXCL3 has been recently shown to contribute to the malignant progression of gastric cancer." (PMID 37193047, 2022). "CXCL3 and CXCL6 were significantly upregulated in gastric cancer tissues compared with normal tissues using the UALCAN database and RT-qPCR." (PMID 37161430, 2023).
Sepsis (7 papers, 2015 to 2025). Sepsis is defined as life-threatening organ dysfunction caused by a dysregulated host response to infection. "An immune cell-specific study has found that MMP9, ARG1, CXCL3, SOCS3, CCR7, and IL-10 are differentially expressed in T cells and monocytes from sepsis patients compared with healthy individuals." (PMID 35721566, 2022).
mastitis (6 papers, 2020 to 2023). Inflammation of breast tissue during lactation or postpartum due to an obstructed duct or infection. "CXCL3 is recognized as a proinflammatory cytokine in dairy cows with experimentally induced S. aureus clinical mastitis." (PMID 34691146, 2021). "The weakened neutrophil functions concomitant with reduced CXCL2 and CXCL3 expression at high environmental temperatures may explain the increased infectious diseases such as mastitis in heat-stressed, dairy cows." (PMID 33374309, 2020). "Thus, immunobiotic L. acidophilus CRL2074 capable of reducing the magnitude of leukocyte migration into the udder, which is reflected in the expression of IL-1α, IL-8, MCP-1, and CXCL3, might influence the clinical course of mastitis." (PMID 32466097, 2020). "In dairy cow studies, the expression of CXCL2 and CXCL3 increased when treated with LPS or lipoteichoic acid (LTA), which are derived from major mastitis pathogens such as E. coli and Staphylococcus aureus in bovine, mammary, epithelial cells." (PMID 33374309, 2020). "Some of the highly connected genes in the purple module have previously been related to mastitis development including NFKBIZ, NFKBIA, CXCL2, GRO1, CXCL3, LPIN1, and DAB2." (PMID 32754201, 2020).
atherosclerosis (5 papers, 2007 to 2025). A disease characterized by the build-up of fatty material and calcium deposition in the arterial wall resulting in partial or complete occlusion of the arterial lumen. "These mice exhibited increased expression of several genes of the CXC chemokine gene cluster, including CXCL1, CXCL2, CXCL3, and Pf4, and classic proinflammatory cytokine genes such as IL-1ß and IL-6, which contribute to atherosclerosis." (PMID 38162500, 2023). "This was evidenced by a consistent macrophage phenotype characterized by significant upregulation of CXCL1, CXCL2, CXCL3, and IL-6, ultimately contributing to the promotion of accelerated atherosclerosis." (PMID 38162500, 2023). "In the lipid and atherosclerosis pathway, lncRNA AC001611.2 expression correlated positively with four genes (MMP3, MMP9, IL-1 and CXCL3) whereas six other lncRNAs correlated negatively with the same genes." (PMID 35224318, 2022). "Overexpression of CXCL3, GK, FPR1, and LST1 was advanced recognition and intervention factors for unstable plaques, which might become targets for atherosclerosis rupture prevention." (PMID 36187340, 2022).
pancreatic ductal adenocarcinoma (5 papers, 2021 to 2025). An infiltrating adenocarcinoma that arises from the epithelial cells of the pancreas. "A recent study showed that CXCL3 was highly upregulated in a certain macrophage and portended poor survival in pancreatic ductal adenocarcinoma." (PMID 34269159, 2021).
preeclampsia (5 papers, 2014 to 2025). Preeclampsia is a hypertensive disorder of pregnancy that is characterized by new-onset hypertension with proteinuria presenting after 20 weeks of gestation, and depending on mild or severe forms may initially present with severe headache, visual disturbances, and hyperreflexia. "Reduced placental CXCL3 expression leads to inadequate extravillous trophoblast invasion and shallow placental implantation, contributing to severe preeclampsia development." (PMID 41463301, 2025). "Severe preeclampsia is characterized by elevated plasma CXCL3 levels but decreased placental CXCL3 expression, potentially representing a compensatory mechanism." (PMID 41463301, 2025). "Our results showed that plasma CXCL3 levels increased, whereas placental CXCL3 expression decreased in the preeclampsia group." (PMID 25485631, 2014). "We compared CXCL3 plasma level and placental expression between the preeclampsia group and the normal pregnant group to determine the relationship between CXCL3 and preeclampsia." (PMID 25485631, 2014). "We considered that low expression of CXCL3 at placenta site resulted in shallow implantation, as a main reason for the onset of preeclampsia." (PMID 25485631, 2014). "The results showed that the plasma CXCL3 level of severe preeclampsia patients was positively correlated with 24 h urinary protein (r2 = 0.660)." (PMID 25485631, 2014). "In summary, a significant abnormality of plasma CXCL3 level and placental CXCL3 expression was discovered in severe preeclampsia; CXCL3 had a function in trophoblast invasion, which indicated its participation in shallow implantation." (PMID 25485631, 2014). "Plasma CXCL3 level (71.31±33.65 pg/mL) in the severe preeclampsia group was significantly higher than that in the normal (28.71±11.91 pg/mL) and mild PE group (30.65±13.00 pg/mL) (P <0.05)." (PMID 25485631, 2014). "Given the similarity between trophoblast and malignant cell invasive properties, CXCL3’s effects on trophoblast invasion may play a key role in preeclampsia pathogenesis." (PMID 41463301, 2025). "Furthermore, in preeclampsia, activation of CXCL3 by endogenous factors promotes trophoblast invasion, migration, and proliferation in human trophoblasts and is critical to the pathogenesis of preeclampsia." (PMID 37445610, 2023). "ELISA was used to detect CXCL3 plasma levels on preeclampsia and normal pregnant groups." (PMID 25485631, 2014). "In addition, placenta CXCL3 expression in severe preeclampsia was significantly lower than those in normal and mild PE groups." (PMID 25485631, 2014). "The plasma CXCL3 level in preeclampsia was significantly higher than that in normal pregnancy." (PMID 25485631, 2014). "In addition, relativity between CXCL3 expression and important clinical indexes in severe preeclampsia suggested that CXCL3 expression level was related to preeclampsia severity." (PMID 25485631, 2014). "However, whether CXCL3 stimulates trophoblast invasion as a key process of preeclampsia pathogenesis remains largely unknown." (PMID 25485631, 2014). "Therefore, we presumed that CXCL3 was involved in preeclampsia pathogenesis." (PMID 25485631, 2014). "Therefore CXCL3 might be involved in severe preeclampsia pathogenesis." (PMID 25485631, 2014). "Women with preeclampsia show increased circulating levels of CXCL10, CXCL11, CXCL12, and CXCL3." (PMID 41463301, 2025). "However, the source of increased CXCL3 in preeclampsia plasma was not clear, which mayact as compensatory role during pathogenesis in other parts." (PMID 25485631, 2014).
autoimmune disease (4 papers, 2017 to 2023). A disorder resulting from loss of function or tissue destruction of an organ or multiple organs, arising from humoral or cellular immune responses of the individual to their own tissue constituents. "It has been widely reported in the literature that many cytokine and chemokine genes (e.g., TNF-a, IL-8, CXCL2, CXCL3, CXCL10, LIF, IL-17C and IL-23A) are the basis of autoimmune disorder pathways that are characterized by inflammation." (PMID 28099447, 2017). "In autoimmune diseases, it was found TCRαβ+ DNT cells might arise from CD8+ T cells and displayed a distinct cytokine production profile by producing proinflammatory mediators that include IL-1β, IL-17, IFN-γ, CXCL3, and CXCL2." (PMID 36443691, 2022).
breast invasive carcinoma (4 papers, 2021 to 2024). "For the chemokine family genes, CXCL3, CXCL5, and CXCL6, gene expression was positively correlated with dendritic cell infiltration in breast invasive carcinoma-Luminal A patients." (PMID 39201290, 2024). "This was observed for CXCL1 and CXCL6 in breast invasive carcinoma, PPBP in kidney chromophobe, CXCL3 in kidney renal papillary cell carcinoma, CXCL6 in pancreatic adenocarcinoma, CXCL6 in thyroid carcinoma, and CXCL3 in thymoma." (PMID 37686093, 2023). "However, in patients with Luminal A breast invasive carcinoma, there was a negative correlation found between ESR1 and CXCL3, CXCL5, and CXCL6 gene expression; and in Her-2 patients, the same relationship was seen between ESR1 and CXCL6." (PMID 39201290, 2024).
glioblastoma (4 papers, 2015 to 2024). The most malignant astrocytic tumor (WHO grade IV). "Notably, both CXCL3 and CXCL5 were identified as hub genes, indicating the significant involvement of the CXCR2 signaling pathway in the progression of glioblastoma." (PMID 38365809, 2024). "Moreover, Kammerer and co-workers observed significant upregulation of inflammation-related genes, including CXCL2, CXCL3, IL1A, and IL6 receptor (IL6R)) after non-lethal 5-ALA-PDT in a panel of prostate and glioblastoma cell lines." (PMID 26705830, 2015).
liver cancer (4 papers, 2021 to 2025). An epithelial or non-epithelial malignant neoplasm that arises from the liver. "This study aimed to investigate the expression and function of CXCL3 in liver cancer and to elucidate its underlying mechanisms." (PMID 41259383, 2025). "Collectively, these findings suggest that elevated CXCL3 expression in liver cancer is linked to poor prognosis, immune cell recruitment, CXCR2 ligand co-expression, and activation of tumor-related immune pathways." (PMID 41259383, 2025). "RNA sequencing data revealed that CXCL3 expression was significantly upregulated in liver cancer tissues compared to normal liver tissues." (PMID 41259383, 2025). "In summary, this study demonstrates a strong association between elevated CXCL3 expression and the accumulation of immune cells and CXCR2-associated chemokines within the tumor microenvironment of liver cancer." (PMID 41259383, 2025). "Immunohistochemistry results demonstrated notably higher CXCL3 expression in liver cancer tissues compared to that in normal liver tissues (P < 0.01)." (PMID 41259383, 2025). "Moreover, migration assays showed that silencing of CXCL3 led to a marked decrease in the migratory ability of the liver cancer cells." (PMID 41259383, 2025). "Moreover, both Transwell and wound healing (scratch) assays demonstrated that CXCL3 overexpression enhanced the migratory ability of the liver cancer cells." (PMID 41259383, 2025). "Taken together, these findings suggest that CXCL3 may facilitate the malignant progression of liver cancer by regulating the expression of CXCR2 ligands and coordinating immune cell recruitment within the tumor microenvironment." (PMID 41259383, 2025). "Since both CXCL3 and CXCL5 signal through CXCR2, it is plausible that CXCL3 may also promote liver cancer progression via CXCR2-dependent pathways." (PMID 41259383, 2025). "Moreover, Transwell migration assays revealed that exogenous CXCL3 at the same concentration range (2–30 ng/mL) enhanced the migratory capacity of all three liver cancer cell lines." (PMID 41259383, 2025). "In alignment with these observations, the present study revealed that CXCL3 expression is significantly elevated in liver cancer tissues and is associated with more advanced clinical staging and reduced overall survival, indicating that CXCL3 may contribute to liver cancer development." (PMID 41259383, 2025). "Importantly, the tumor-promoting effects of CXCL3 were significantly suppressed by treatment with the mechanistic target of rapamycin (mTOR) inhibitor Torin 1, supporting the notion that targeting this pathway may provide therapeutic benefit in liver cancer." (PMID 41259383, 2025). "In our study, we observed a positive correlation between CXCL3 expression and infiltration of macrophages, neutrophils, B cells, CD4-positive T cells, CD8-positive T cells, and dendritic cells in liver cancer tissues." (PMID 41259383, 2025).